PRDM11 (PR/SET domain 11)
Description:
May be involved in transcription regulation.
Synonyms: PFM8
Tractability: PROTAC: UniProt records ubiquitination sites on it.
Target class: Enzyme; Transferase
Gene: Protein-coding gene on chromosome 11 (45,095,806 to 45,235,110, forward strand). Ensembl gene ENSG00000019485.
Subcellular location: Nucleus; Cytoplasm
Gene Ontology:
Molecular function: protein binding; chromatin binding; DNA-binding transcription factor activity; RNA polymerase II cis-regulatory region sequence-specific DNA binding
Biological process: negative regulation of cell growth; negative regulation of DNA-templated transcription; positive regulation of DNA-templated transcription; positive regulation of fibroblast apoptotic process; regulation of cell cycle; regulation of MAPK cascade; cell fate commitment; regulation of transcription by RNA polymerase II
Cellular component: cytoplasm; cytosol; nucleus
Genetic constraint (gnomAD): Loss-of-function variants: 20 observed, 100.09 expected, observed/expected ratio (o/e) 0.2, 90% interval 0.14 to 0.29. The upper end of that interval is the gene's LOEUF score, 0.29, which puts it in group 1 of 6, group 1 being the genes least tolerant of losing a copy. Missense variants: 1,120 observed, 1,580.5 expected, observed/expected ratio (o/e) 0.71, 90% interval 0.67 to 0.74. Synonymous variants: 590 observed, 651.22 expected, observed/expected ratio (o/e) 0.91, 90% interval 0.85 to 0.97.
Homologues: Orthologues: chimpanzee PRDM11 (99% identical), macaque PRDM11 (99% identical), dog PRDM11 (97% identical), pig PRDM11 (96% identical), guinea pig PRDM11 (95% identical), mouse Prdm11 (94% identical), rat Prdm11 (94% identical), rabbit PRDM11 (91% identical), tropical clawed frog prdm11 (77% identical), zebrafish prdm11 (60% identical). Paralogues in human: PRDM7 (8% identical).
Diseases named in the same sentence as PRDM11 in open-access papers:
PRDM11 is named in the same sentence as 9 diseases in open-access papers, as found by Europe PMC text mining. Sharing a sentence is not in itself a finding about the gene and the disease. The quoted sentences say what the papers report.
B cell lymphomas (1 paper, 2015). "Prdm11, a tumour suppressor gene in MYC-driven B cell lymphomas and involved in transcriptional regulation, was recently associated with pulmonary function in humans in a genome-wide association study (GWAS)." (PMID 26263558, 2015).
diffuse large B-cell lymphoma (1 paper, 2023). "In diffuse large B-cell lymphomas (DLBCLs), the study showed that the overexpression of PRDM11 (PR-domain family member Prdm11) could induce apoptosis in the Eμ-Myc mouse model, then, the DLBCLs patients with low levels of PRDM11 correlate with shorter overall survival." (PMID 36755810, 2023).
hyperthyroidism (1 paper, 2021). Overactivity of the thyroid gland resulting in overproduction of thyroid hormone and increased metabolic rate. "It is present in “pattern III” of expression, together with PRDM11 whose SNP are reported to be correlated with extreme phenotypes for thyroid function (hyperthyroidism)." (PMID 34249923, 2021).
lung diseases (1 paper, 2023). "Additionally, PRDM11 was also identified as a novel locus associated with forced vital capacity, which could be a new target for lung diseases in a genome-wide association analysis." (PMID 36755810, 2023).
cancer (2 papers, 2023 to 2024). A tumor composed of atypical neoplastic, often pleomorphic cells that invade other tissues. "However, the mRNA expression levels of PRDM1, PRDM2, PRDM8, and PRDM11 were higher in normal and cancer tissues." (PMID 39468462, 2024). "Intriguingly, we found that the protein expression levels of MECOM, PRDM5, PRDM10, and PRDM11 were generally higher in UCEC tissue compared to normal tissue, while the expression of PRDM1 was diminished in cancer tissue." (PMID 39468462, 2024). "The H-score levels of the protein expression levels of MECOM and PRDM11 were significantly higher in UCEC tissue, whereas the H-scores of PRDM1 and PRDM12 were weakened or undetectable in cancer tissue." (PMID 39468462, 2024). "For instance, we use it to identify novel cancer-related genes, i.e. PRDM11, C9orf72, MINDY3, and H4C6, that could have an important role in the studied cancer types." (PMID 37084262, 2023). "However, the promoter methylation levels of PRDM3, PRDM4, PRDM6, PRDM11, and PRDM12 do not show significant differences across all cancer types." (PMID 39468462, 2024).
PRDM11 also shares sentences with these, for which no sentence is quoted: hypothyroidism (2 papers); tumor (2); glioma (1); uterine corpus endometrial carcinoma (1).